IL6 (interleukin 6)
Diseases named in the same sentence as IL6 in open-access papers (continued):
Sharing a sentence is not in itself a finding about the gene and the disease.
Obesity (continued). "Gouranton and his co-workers demonstrated in their study that lycopene had a moderating effect on the formation of IL-1β, IL-6 and TNF-α in adipose tissue and eventually might prevent or reduce the incidence of obesity-related diseases including insulin resistance." (PMID 36826001, 2023). "Besides, PQQ also could protect hepatocyte from lipotoxicity and inflammation followed obesity via down-regulating the level of pro-inflammatory cytokines (NLRP3, IL-6, TNF and IL-1β)." (PMID 37935689, 2023). "High levels of insulin-like growth factor 1 (IGF1) and insulin in obesity downregulate Glycogen synthase kinase 3 beta (GSK3B) activity by phosphorylating its serine residue, thereby altering the IL-17 signaling pathway, including upregulation of CXCL1, CCL20, and IL-6 expression." (PMID 37680632, 2023). "The analysis of other inflammatory markers may provide more information about the chronic and low-grade systemic inflammation characteristic of obesity since other authors have already found a relationship between tumor necrosis factor-α (TNF-α), adipokines, and interleukin-6 and BMI20." (PMID 37474543, 2023). "Moreover, HIIT-induced IL-10 overexpression may suppress IL-β, IL-6, and TNF-α in mononuclear cells challenged with lipopolysaccharide and the transcription of IL-8 in polymorphonuclear leukocytes in individuals with obesity." (PMID 37608837, 2023). "During obesity, the energy excess leads to adipose expansion generating hypertrophic adipocytes that produce a wide variety of proinflammatory molecules, such as monocyte chemoattractant protein-1 (MCP-1), TNF-α, IL-1β, and IL-6 that activate and attract the immune system cells." (PMID 37139092, 2023). "Obesity induces adipocyte dysfunction, with adipokine secretion and macrophage activation leading to proinflammatory cytokine such as tumor necrosis factor alpha (TNF-α) and interleukin-6 (IL-6) production and the release of anti-inflammatory adipokines such as adiponectin reduction." (PMID 37215204, 2023). "Notably, mice lacking IL-6 exhibit obesity and glucose intolerance, indicating the beneficial role of muscle-derived IL-6 in metabolic regulation." (PMID 37755259, 2023). "The following part of the review describes the key roles of adiponectin, leptin, resistin, IL-6, MCP-1 and PAI-1 recognized to be involved in the physiopathology of obesity and cited as relevant targets for limiting metabolic and vascular complications in obesity." (PMID 38136564, 2023). "Second, the level of CRP is higher in children with obesity, and chronic inflammation is a characteristic of obesity, as adipocytes trigger metabolic signals that induce inflammation as indexed by increases in the levels of CRP and other inflammatory markers such as IL6 with disruption of sleep." (PMID 37305117, 2023). "However, after NSPT, the reduction of IL-6 levels is statistically significant in patients with obesity in a 3-month follow-up period, while no such impact is observed in normal-weight individuals with periodontitis." (PMID 37798684, 2023). "IL-6 induces hepatocytes to produce and release inflammatory molecules, c-reactive protein (CRP) that indicates liver-caused systemic inflammation which controls obesity regardless of race and gender." (PMID 37229273, 2023). "Baseline results of pro-inflammatory biomarkers, including serum interleukin (IL)-6, serum and gingival crevicular fluid (GCF), tumor necrosis factor (TNF)-a, serum C-reactive protein (CRP)/hs-CRP, and serum and GCF resistin, were higher in obesity subjects than in normal weight subjects." (PMID 37798684, 2023). "Acute IL-6 infusion of mice leads to insulin resistance without obesity." (PMID 36230963, 2022). "Furthermore, pre-pregnancy obesity and several lifestyle factors, including a diet rich in meat and processed foods, correlate directly with high concentrations of circulating inflammatory biomarkers, such as CRP and IL-6." (PMID 35270396, 2022).
Obesity (continued). "The results on the survival rate and occurrence of severe proteinuria in this study suggest that obesity induced by HFD significantly reduced the therapeutic effect of methylprednisolone in SLE, in a process probably involving proinflammatory cytokines such as IL-6, MCP-1 and TNF-α, and adipokines." (PMID 36323742, 2022). "Also obesity is recognized as a state of chronic inflammation with increased circulating pro-inflammatory cytokines tumour necrosis factor (TNF)-α, interleukin (IL)-1β and IL-6." (PMID 36614882, 2022). "MEF explants secreted high levels of several visceral‐associated inflammatory cytokines thought to be important for the negative adipose–muscle signalling in obesity, notably interleukin 6 (IL‐6), monocyte chemoattractant protein 1 (MCP‐1), tumour necrosis factor α (TNF‐α) and IL‐1β." (PMID 35844058, 2022). "In addition, the expression levels of hepcidin increased in visceral adipose tissue of HFD-induced obesity mice, in parallel with IL-6, which occurred in macrophages of adipose tissue, not in adipocytes." (PMID 36335331, 2022). "As IL-6 and CRP reflect the degree of metabolic inflammation in obesity, our data might suggest that Parasutterella mediates its negative effects on host glucose metabolism – at least in the periphery – via direct metabolic effects rather by influencing the innate immune system." (PMID 35435797, 2022). "Obesity is forming fat tissue with angiogenesis expressing inflammatory factors such as tumor necrosis factor alpha (TNF-alpha), monocyte chemoattractant protein-1 (MCP-1), interleukin 6 (IL-6) and so on which enhance chronic inflammation and will lead to higher risks of cancer." (PMID 36115905, 2022). "In obesity, visceral adipose tissue downregulates the expression of anti-inflammatory adipocytokines, such as adiponectin, that protects the vascular endothelium and upregulates the expression of several proinflammatory mediators, including C-reactive protein (CRP) and interleukin-6 (IL-6)." (PMID 36258233, 2022). "Mme activation did not increase LPS-induced IL-6 or TNFα, suggesting that our innate immune memory model, and potentially weight cycling, is immunologically distinct from models of simple obesity." (PMID 36713396, 2022). "Circulating levels of IL-6 are significantly higher in patients with overweight (BMI range: 25–29.9 kg/m2) and obesity (BMI > 30 kg/m2), and correlate positively with BMI in patients with grade III obesity, and negatively with serum HDL-C in patients with grade II obesity." (PMID 36430774, 2022). "Thus, acupuncture may affect the regulation of obesity by inhibiting the activation of TLR4 via HMGB1 and thus downregulating NF-κB/IL-6 pathway." (PMID 36105933, 2022). "These excess calories can cause chronic low-grade inflammation, as adipocyte hypertrophy in obesity results in increased infiltration of macrophages into adipose tissue, which secrete inflammatory cytokines, such as tumor necrosis factor-alpha (TNF-α) and interleukin 6 (IL-6)." (PMID 36364929, 2022). "Since all of our study patients have obesity, this might explain the lack of significance in IL-6 level between our two study groups according to OSA severity." (PMID 36017324, 2022). "In addition, many hormones and cytokines altered with obesity may influence ADPKD progression, including increased levels of insulin, insulin-like growth factor 1 (IGF-1), leptin, TNF-α, and IL-6, as well as decreased adiponectin." (PMID 35350649, 2022). "However, a meta-analysis of RCTs in patients with T2DM and overweight or obesity reported that vitamin D supplementation significantly decreased circulating CRP concentrations but did not affect TNF-α or IL-6 concentrations." (PMID 35893929, 2022).
Obesity (continued). "Obesity-induced insulin resistance was found to be improved in TNF-α knockout mice, and elevated levels of TNF-α were observed to enhance the production of the pro-inflammatory factors MCP-1 and IL-6, as well as downregulating the expression of anti-inflammatory adipokines such as adiponectin." (PMID 35807921, 2022). "Nevertheless, IL-6 affects insulin-degrading enzyme expression and activity in the liver and skeletal muscle tissues, and modulation of this enzyme may contribute to T2DM and obesity." (PMID 35620114, 2022). "In parallel, there is increasing evidence that pro-inflammatory signals like TNF-α, IL-1β, and IL-6 represent important components of the thermogenic potential of BAT and may lead to their altered capacity for energy expenditure and glucose uptake in obesity." (PMID 35436959, 2022). "Although a lack of a significant association between the circulating IL-6 levels and GDM has been observed in some studies, an elevated concentration of IL-6 has been frequently reported in GDM patients, even regardless of obesity." (PMID 36498901, 2022). "Moreover, adipose tissues secret a number of other cytokines, including interleukin-6 (IL-6), tumor necrosis factor α (TNFα), and monocyte-chemoattractant protein-1 (MCP-1), which may also contribute to obesity-promoted cancer initiation and progression." (PMID 33535537, 2021). "However, in the hypothalamus, the putative neurogenic actions of IL6 have never been explored, and its potential to balance energy intake can be an approach to prevent or attenuate obesity." (PMID 34465367, 2021). "Obesity-related metabolic disorders elicit systemic low-grade inflammation by increasing the levels of proinflammatory factors, such as monocyte chemoattractant protein-1 (MCP-1), CD11c, tumor necrosis factor-α (TNF-α), leptin, lipopolysaccharide binding protein (LBP), and interleukin-6 (IL-6)." (PMID 34579036, 2021). "In our present study, we found that after the construction of obesity-induced IR animal model, in total CD4+ T cells, Treg cells were reduced, Th17 cells were increased, levels of markers TGF-β1 and IL-10 were downregulated, and those of IL-17 and IL-6 were upregulated." (PMID 33781239, 2021). "Moreover, the studies have shown that a decreased concentration of adiponectin and interleukin 10 and an increased concentration of leptin, resistin, interleukin 6, and MCP-1 could be a potential marker of obesity and its accompanying disorders." (PMID 34769133, 2021). "Our data do not support a link of inflammation (as determined by TNFα, IL‐6, procalcitonin and CRP values) to BCAA concentrations, thus the mechanisms underlying increased BCAA levels in obesity remain unclear." (PMID 33058486, 2021). "Importantly, obesity-induced metabolic inflammation produces CRP, as a proinflammatory biomarker, and adipokines, including tumor necrosis factor-alpha (TNF-α) and interleukin (IL)-6, which further propagate inflammation." (PMID 34055004, 2021). "However, the release of IL-6 could be different in our model given that macrophages are the main producers of IL-6 and abundantly infiltrate the VAT in obesity." (PMID 34203452, 2021). "IL-6 can induce expression of C reactive protein (CRP), which are together used as clinical markers of inflammation and risk of T2DM development, independent of obesity." (PMID 33670215, 2021). "Visceral adipose tissue (VAT) produces higher inflammatory cytokines (TNF-α, IL-6, and IL-1β) in comparison to subcutaneous adipose tissue, suggesting that cytokine storm in COVID-19 infection could be independent of obesity." (PMID 34220807, 2021). "This is not surprising, as cytokines of innate immunity such as interleukin 6 (IL-6) and tumor necrosis factor alpha (TNF-α) may be produced by adipocytes as a result of low-grade inflammation of white adipose tissue which characterizes obesity." (PMID 33809270, 2021).
Obesity (continued). "In this way, obesity and mitochondrial dysfunction dysregulate the production of WAT-derived circulating adipokines such as interleukins (IL)-6, IL-1β, and tumor necrosis factor (TNF)-α, which may exacerbate the state of low-grade, chronic inflammation observed in obesity." (PMID 34835983, 2021). "In general, obesity is characterized by chronic inflammation and increased expression and release of proinflammatory neurohumoral factors, including adipokines such as leptin and adiponectin, and proinflammatory cytokines such as tumor necrosis factor-α (TNF-α), interleukin (IL)-1 and IL-6." (PMID 34088886, 2021). "NAFLD, insulin resistance, and obesity increase adipocyte lipolysis and have a stimulatory effect on immune cells such as macrophages and lymphocytes, leading to a chronic state of low-grade inflammation with increased production of proinflammatory cytokines, including TNF-α and IL-6." (PMID 33807573, 2021). "Obesity is present in almost 50% of women with SLE and adipose tissue has the capacity not only to recruit and activate mononuclear cells but also to produce key inflammatory cytokines, such as IL-6, which stimulates the production of CRP and other acute phase proteins by the liver." (PMID 34721392, 2021). "These improvements in insulin markers in the population with obesity are important because are against of obesity pathophysiology, that is characterized by a state of low-grade systemic inflammation due to increased secretion of inflammatory cytokines, such as TNF-α and IL-6." (PMID 34568974, 2021). "Hence, expanded adipocyte mass, overexpression of TNF-α and IL-6 mRNA and protein along with declined expression of PPAR-γ in adipocytes of HFD and sucrose fed rats clearly indicates the development of obesity induced inflammation and thus insulin resistance in them." (PMID 33917607, 2021). "Our current data suggest that boosting intratumoral anti-tumor effector signals, such as CCL5, or blocking pro-inflammatory signals such as GM-CSF and IL-6, could serve as therapeutic options in combination with ICB, particularly in patients with combined obesity and RCC." (PMID 34064933, 2021). "The reduction of the secretion of IL-6 and TNF-α by V. opulus juice was observed in Saos-2 cells, therefore showing that the juice may be important not only for the metabolism of bone tissue but also may delay its demineralization resulting from obesity." (PMID 34279426, 2021). "It has been reported that diet‐induced obesity activates adipose tissue macrophages (ATM) into pro‐inflammatory M1 macrophages that produce a variety of pro-inflammatory cytokines such as TNF‐α and IL‐6, which contribute to the development of diabetes and atherosclerosis." (PMID 33737713, 2021). "The study aimed to follow up on the changes in the peripheral CD4+ T lymphocytes and the pro-inflammatory cytokines; IL-6, TNF-alpha, MCP-1, and IL-10 at baseline and 12 weeks post-surgical intervention by the laparoscopic gastric sleeve (LGS) in morbidly obese patients (class III obesity subjects)." (PMID 33981153, 2021). "Inhibition of IL6 and SOCS3 and facilitation of CNTF could serve as a favorable strategy to enhance insulin action and improve glucose homoeostasis, which are of importance for treating obesity-related disorders for chickens." (PMID 32106651, 2021). "Similarly, neutrophil counts and IL-6 levels were significantly increased in a group of obese adults with severe asthma compared with patients without obesity." (PMID 34835964, 2021). "Furthermore, since adipocytes release proinflammatory markers (TNF-a, IL-6, and CRP), obesity may dysregulate the inflammatory markers and potentiate the inflammatory response, which could lead to higher pain sensitivity." (PMID 34257764, 2021).
Obesity (continued). "The direct molecular factors linking obesity and cancer are not fully understood, but the organ-dependent crosstalk between the adipose tissue and carcinomas via the vascular endothelial growth factor (VEGF), interleukin 6 (IL-6), tumor necrosis factor α (TNFα), and other mechanisms are implicated." (PMID 34638514, 2021). "Metabolic NAFLD complications, obesity, insulin resistance and type 2 diabetes involve a chronic “low-grade inflammation”, resulting in the increase in obesity-related inflammatory molecules, such as: TNF-alpha, IL-1beta, IL-6, IL-1Ra, and C-reactive protein (CRP)." (PMID 33306695, 2020). "To identify signals in fat tissue that might induce YAP/TAZ activation during obesity, we analyzed whether palmitic acid or several cytokines, including TNFα, interleukin (IL)-1β, CCL2, and IL-6 are able to induce YAP/TAZ target gene expression in 3T3-L1 adipocytes." (PMID 33116140, 2020). "For instance, obesity tends to be accompanied by excessive consumption of HFD, and related to a chronic inflammation condition characterized by the increased plasma levels of proinflammatory cytokines such as tumor necrosis factor α (TNF-α), interleukin-6 (IL-6), and interleukin-1 (IL-1)." (PMID 31993071, 2020). "Elevated inflammatory cytokines IL-6 and TNF-α are majorly produced by increased M1 macrophages in obese AT and their altered circulating levels have been reported in patients with overweight and obesity, contributing to a local as well as systemic chronic inflammation." (PMID 32806722, 2020). "During obesity-induced liver inflammation, hypertrophic adipocytes secrete free fatty acid, while several immune cells (including Kupffer cells and hepatic stellate cells (HSC)) produce pro-inflammatory cytokines (TNF-α, IL-6, IL-1β and IL-10) and adipokines (leptin and adiponectin)." (PMID 32948162, 2020). "Recent studies have shown that excess energy intake and endogenous lipolysis of saturated fatty acids might increase the production of proinflammatory cytokines, including IL-6 and MCP-1 as well as activation of NF-κB signaling pathway, which partly contributed to adipocyte inflammation and obesity." (PMID 31630283, 2020). "Finally, we can state that IL-6 and TNF-α are the main players of inflammation in obesity." (PMID 32650509, 2020). "An excessive production of estrogen and inflammatory cytokines such as interleukin (IL)-1, IL-6, and tumor-necrosis factor (TNF) due to elevated fat mass in individuals with obesity may contribute to dysregulated biological processes that support carcinogenesis." (PMID 33287442, 2020). "Obesity has been suggested to promote oxidative stress, as obesity promotes the infiltration and activation of macrophages and monocytes into adipose tissue which in turn release elevated levels of pro-inflammatory adipokines, such as tumor necrosis factor alpha (TNF-a) and interleukin-6 (IL-6)." (PMID 32231008, 2020). "Most of the myokines measured were regulated by acute exercise (FGF21, IL-6, IL-8, IL-15, and IL-18), and some were released at different levels in plasma over the 24 h in the group of women with obesity in comparison to the non-obese group (SPARC, IL-8, and IL-13)." (PMID 32132925, 2020). "Since IL-6 from the serum can ultimately reach placental tissues, we speculated that the axis of “WAT—maternal serum—placental labyrinth” represents a possible route of obesity-induced placental inflammation and EC damage leading to placental insufficiency." (PMID 31979004, 2020). "Interestingly, Biocarta also found significant overrepresentation in two well-known anti-inflammatory pathways: the PPARγ-related obesity pathway (Systemic name M22017) and the IL-10/JAK/STAT signaling pathway that result in the repression of TNFα, IL-1, and IL-6 (Systemic name M6778)." (PMID 33256749, 2020).